USP12 (ubiquitin specific peptidase 12)
Diseases named in the same sentence as USP12 in open-access papers (continued):
Sharing a sentence is not in itself a finding about the gene and the disease.
tumor (continued). "As expected, 889-S1 tumours were sensitive to PD-1 blockade treatment; USP12 silencing, however, substantially desensitized tumours to anti-PD-1 therapy, as evidenced by tumour incidence and volume." (PMID 34381028, 2021). "Tumour growth was significantly enhanced in cells with USP12 shRNA expression compared with control cells." (PMID 34381028, 2021). "Next, we sought to investigate which signalling pathway was mainly responsible for USP12 downregulation in tumour cells by utilizing the inhibitors targeting the main pathways downstream of the oncogenic mutations or constitutively activated in NSCLC." (PMID 34381028, 2021). "Bioinformatics analyses of human NSCLC databases predicted that NSCLC patients with high USP12 expression in tumours would be more responsive to ICB therapy." (PMID 34381028, 2021). "Intriguingly, enhanced PD-L1 expression was also detected in CD45− cells in shUSP12 tumours, indicating a role of USP12 in modulating this immunoregulatory molecule in tumour cells and non-hematopoietic stromal cells in vivo." (PMID 34381028, 2021). "We further analysed the expression patterns of these genes in human NSCLC using the TCGA-LUAD and GSE31210 databases and found that only USP12 was preferentially downregulated in both NSCLC tumours and tumourigenic KrasG12D;SV40-LT MEFs." (PMID 34381028, 2021). "NF-κB reporter assays confirmed USP12-mediated suppression of NF-κB signalling activity in tumour cells." (PMID 34381028, 2021). "Exogenous USP12 expression markedly increased the survival of mice and decreased overall tumour number or burden in the entire lung compared with that of control mice." (PMID 34381028, 2021). "Together, the results from genetically engineered mouse and transplanted tumour models suggest that USP12 negatively regulates lung tumour growth." (PMID 34381028, 2021). "USP12 downregulation in tumour cells accelerates PPM1B ubiquitination and degradation and therefore promotes NF-κB activity in orchestrating the TME." (PMID 34381028, 2021). "We found that USP12 downregulation caused insufficient deubiquitination of PPM1B and thereby facilitated tumour growth by promoting the generation of the protumourigenic milieu." (PMID 34381028, 2021). "In the mouse KrasG12D-driven lung tumour model, we further confirmed USP12 downregulation at both the mRNA and protein levels in tumour specimens compared with normal adjacent tissues." (PMID 34381028, 2021). "The tumour suppressive function conveyed by USP12 is virtually related to the control of protumourigenic chemokine expression." (PMID 34381028, 2021). "Moreover, we discuss the influence of USP12 on tumorigenesis, tumor immune microenvironment (TME), disease, and related signaling pathways." (PMID 37752518, 2023). "Therefore, the study of USP12 in NF-κB signaling contributes to the in-depth understanding of the tumor immune microenvironment, providing new insights into immunotherapy." (PMID 37752518, 2023). "Therefore, the combinatory effects of the aberrantly expressed chemokines on growth and ICB response of tumours with USP12 downregulation are possibly fulfilled through regulating different types of immune cells." (PMID 34381028, 2021). "Moreover, coexpression of Cxcl1 and Ccl2 efficiently attenuated activation of CD8+ and CD4+ T cells in tumour cells ectopically expressing USP12, as evidenced by the changes in the frequencies of TNF-α+IFN-γ+ cells in the populations." (PMID 34381028, 2021). "Thus, our results illustrate that USP12, as a convergent regulator downstream of tumour-driven events in NSCLC, plays a role in reprogramming the TME and influences the tumour response to immune checkpoint blockade." (PMID 34381028, 2021). "GSEA validated an inverse correlation between USP12 expression and tumour angiogenesis in NSCLC." (PMID 34381028, 2021). "Accordingly, we found that silencing USP12 enhanced PD-L1 expression in tumour cells." (PMID 34381028, 2021).
tumor (continued). "However, the clinical relevance of USP12 in human tumour development and progression, as well as its potential impacts on tumour immunotherapy, remain elusive." (PMID 34381028, 2021). "Importantly, the inhibitory effects on tumour growth and the alterations in TME composition caused by USP12 overexpression were efficiently rescued by CXCL1 and CCL2." (PMID 34381028, 2021). "Similarly, co-expression of Cxcl1 and Ccl2 in 889-S1 tumour cells substantially increased tumour incidence and growth in the presence of USP12 overexpression, suggesting the importance of the tumour-extrinsic effects controlled by USP12." (PMID 34381028, 2021). "We also investigated whether USP12 expression in tumour cells might modulate macrophage polarization." (PMID 34381028, 2021). "Similarly, combined expression of Cxcl1 and Ccl2 in 889-S1 tumour cells substantially counteracted the inhibitory effects of USP12 on the TAM infiltration and their PD-L1 expression as well as on CD31+ cell presence." (PMID 34381028, 2021). "Taken together, these data suggest that downregulation of USP12 in NSCLC may help establish a tumour microenvironment that is favourable for tumour growth by facilitating protumourigenic chemokine expression." (PMID 34381028, 2021). "To explore the molecular mechanism underlying USP12-mediated tumour suppression, we analysed the transcriptional profiles of lung tumour cells with or without USP12 overexpression by RNA-seq." (PMID 34381028, 2021). "In this regard, increased CXCL8 production contributed from increased TAM presence and direct activation of CXCL8 transcription in tumours with USP12 downregulation may greatly contribute to resistant phenotype to PD-1 blockade." (PMID 34381028, 2021). "Functionally, we show that WDR48 and USP12 suppress proliferation of tumor cells." (PMID 24145035, 2013). "Ubiquitin-specific peptidase 12 (USP12), one of the major members of the deubiquitinating enzyme family, participates in various biological functions, such as cell proliferation and differentiation, apoptosis, neurodegeneration, tumor promoting, and antiviral immune responses." (PMID 37410794, 2023). "Moreover, USP12 has a close connection with the tumor immune microenvironment." (PMID 37752518, 2023). "Furthermore, USP12 inhibition substantially induces mouse tumour resistance to PD-1 blockade." (PMID 34381028, 2021). "In addition to human LUADs, decreased expression of USP12 was found in LUSC tumours." (PMID 34381028, 2021). "Overall, these results reveal a significant prevalence of USP12 downregulation in human NSCLC and suggest that USP12 downregulation may represent a convergent response to the signals driven by oncogenic mutations or their surrogates in tumour cells." (PMID 34381028, 2021). "Finally, we suggest that USP12 downregulation in tumours may account for the impaired response to anti-PD-1 treatment in a mouse tumour model." (PMID 34381028, 2021). "At the same time, USP12 can affect INF-γ stability and reduce the anti-tumor immune capacity in the TME." (PMID 39759114, 2025). "USP12 can inhibit NF-κB signaling activity to regulate the production of chemokines (such as CXCL8 and CXCL1), which then modulate the tumor immune microenvironment to alter the response of NSCLC to immunotherapy." (PMID 37752518, 2023). "Patients receiving intensive chemotherapy of their NBT showed significantly reduced tumor tissue expression of USP24, USP34, MINDY2, USP8, JOSD1, USP52, and USP12 when compared to the observation group." (PMID 37892185, 2023). "It has also been described that USP12 is downregulated in NSCLC and able to regulate tumor chemokine secretion or induce macrophage recruitment and decrease T cell activity to promote tumor microenvironment development." (PMID 37752518, 2023). "Deubiquitinating and stabilizing p65 with ubiquitin-specific peptidase 12 (USP12) impair infiltration and suppressive function of M-MDSCs, thus increasing CD8+ T-cell response and decelerating tumor growth." (PMID 37443711, 2023).
tumor (continued). "Relative to normal tissues, USP12 expression was elevated at both mRNA and protein levels in HCC tumor tissue samples." (PMID 37752518, 2023). "In contrast, two down-regulated genes in OVCAR-3 and OAW-42 cells, the USP12 and PTK2, reported to promote tumor cell growth, both exhibited a weak positive correlation with an adverse OS, (HR = 1.17, p = 0.018) and (HR = 1.18, p = 0.016), respectively." (PMID 36077645, 2022). "The downregulated USP12 transcription in tumours was also demonstrated in other NSCLC databases and broadly present in the tumours of the patients at different stages." (PMID 34381028, 2021). "Using 889-S1 cells that express high levels of MHC I upon IFN-γ stimulation and display more aggressive tumour growth in nude mice than in C57BL/6 mice, we tested the impact of USP12 inhibition on the efficacy of anti-PD-1 therapy." (PMID 34381028, 2021). "Our results provide evidence that USP12 downregulation, which is at least partially due to PI3K-AKT-mTOR hyperactivation, functionally induces tumour cell resistance to PD-1 blockade in mice." (PMID 34381028, 2021). "Collectively, our study used several models to underscore the importance of USP12 downregulation in creating a TME that promotes NSCLC development and potentially contributes to tumour resistance to immunotherapy." (PMID 34381028, 2021). "UAF1/USP1, UAF1/USP12, and UAF1/USP46 complexes play vital roles in DNA repair processes and tumor pathogenesis." (PMID 33247121, 2020). "Together, our results reveal WDR48 and USP12 as novel PHLPP1 regulators and potential suppressors of tumor cell survival." (PMID 24145035, 2013). "We demonstrated that the WDR48·USP12 complex deubiquitinates and regulates PHLPP1 levels, which is essential for their possible tumor suppressor function." (PMID 24145035, 2013). "USP12, which is one of the major members of the ubiquitin-specific peptidase (USP) family, participates in various biological functions, such as cell proliferation and differentiation, apoptosis, neurodegeneration, and tumor-promoting." (PMID 37410794, 2023). "The UAF1/USP12 complex deubiquitinates PHLPP1 and suppresses the proliferation of tumor cells." (PMID 36988464, 2023). "On the other hand, Ingenuity pathway analysis software (IPA, Qiagen) identified three genes with notably decreased mRNA levels upon chemerin treatment, USP12, CAT and PTK2 (FAK), which exert tumor-promoting effects and stimulate proliferation of cancer cell lines in vitro." (PMID 36077645, 2022). "Consistently, ectopic expression of the myristoylated form of AKT1 (myr-AKT1) significantly repressed USP12 expression in both human and mouse tumour cells; knockdown of endogenous AKT1 or AKT2, the two major isoforms of AKT, induced higher levels of USP12 than did the control treatment." (PMID 34381028, 2021). "Accordingly, the overwhelming majority of tumour tissues from NSCLC patients (17/18 cases) exhibited lower protein levels of USP12 than the corresponding non-tumour tissues." (PMID 34381028, 2021). "Our data indicates that inhibition of USP12 and USP46 activity with galeterone, or other compounds may be a very effective anti-tumour strategy, however galeterone effects in those PC patients expressing AR V may be limited." (PMID 29861848, 2018). "In vitro macrophage recruitment experiments showed that CM from tumour cells ectopically expressing USP12 but not USP12-C48S induced less migration of bone-marrow-derived macrophages (BMDMs) than the supernatant of control cells, whereas CM from LLC-shUSP12 cells exacerbated the BMDM migration." (PMID 34381028, 2021). "Moreover, a negative correlation between CD274 (PD-L1) and USP12 transcript levels were found in NSCLC tumours." (PMID 34381028, 2021). "Thus, WDR48·USP12, being a deubiquitinase complex and a positive regulator of PHLPP1 stability, might function as a tumor suppressor complex as well." (PMID 24145035, 2013).
tumor (continued). "To further detect whether the alterations in the chemokine profiles were critical in USP12-mediated control of tumour growth, we overexpressed Cxcl1 combined with or without Ccl2 into mouse lung tumour cells and found that LLC cells, when overexpressing Cxcl1, grew more rapidly than control cells." (PMID 34381028, 2021). "Furthermore, overexpression of USP12 but not of USP12-C48S inhibited LLC and 889-S1 tumour growth in immune-competent mice, indicating that the deubiquitinase activity was required for USP12 to exert its tumour suppressive function." (PMID 34381028, 2021).
cancer (14 papers, 2015 to 2026). A tumor composed of atypical neoplastic, often pleomorphic cells that invade other tissues. "PHLPP1, histone H2A, and H2B have been identified as substrates of both USP12 and USP46, suggesting that USP12 and USP46 are associated with AKT signaling in cancer cells and transcription activation in Xenopus embryo." (PMID 39482856, 2025). "Studies have demonstrated that USP12 facilitates in the advancement of cancer by deubiquinating substrates." (PMID 38605077, 2024). "USP12 participates in the development of various diseases, such as neurodegeneration, cancer and inflammatory diseases." (PMID 37410794, 2023). "The pathologic function of USP12 in other types of cancer, especially in terms of TME regulation, remains elusive." (PMID 34381028, 2021). "It has been reported that USP12 is involved in the development of cancer, including prostate cancer and other cancers." (PMID 34759262, 2021). "CCL2, another chemokine downregulated by USP12, also contributes to the recruitment and polarization of cancer-promoting myeloid cells." (PMID 34381028, 2021). "Similarly, USP12 has also been studied in tumors and identified as one of the 12 most frequently overexpressed cancer-related genes located near amplified super enhancers, and therapeutic approaches targeting USP12 deserve more attention." (PMID 37752518, 2023). "Hence, the link between USP12/46 and Itgb1 stability may well have a contributory role in the course of different cancer entities, originating of both epithelial and blood origin, and call for the exploration of compounds that inhibit the activity of the DUB complex." (PMID 39506038, 2024). "This manuscript provides a proof of principle for USP12 and USP46 targeted inhibition in cancer therapy." (PMID 29861848, 2018). "Beyond AKT, USP12 also stimulates STAT1 signaling and USP46 regulates the cell cycle through stabilizing the CRL4Cdt2 E3 ubiquitin ligase complex, which promotes proliferation of HPV-transformed cancers." (PMID 41533576, 2026).
infection (4 papers, 2019 to 2023). The state of being infected such as from the introduction of a foreign agent such as serum, vaccine, antigenic substance or organism. "HDAC5, KDM2B, EZH1, PRDM2, SETMAR, SMYD4 and USP12 were differentially expressed at all time points post-infection (excluding 2 hpi)." (PMID 30728374, 2019). "Hence, we used a recombinant L. monocytogenes strain expressing chicken ovalbumin (LM-OVA) infection model to investigate the USP12 knockdown effects on the CD4+ T cell phenotype." (PMID 33941870, 2021). "Our study results showed that USP12 activated CD4+ T cell signaling, and targeting USP12 might help develop therapeutic interventions for treating inflammatory diseases or pathogen infections." (PMID 33941870, 2021). "Thus, USP12-targeted therapies offer promise as therapeutic strategies for inflammatory diseases or for resolving pathogen infection." (PMID 33941870, 2021). "Our findings suggest that USP12 might be a potential drug target for developing therapeutic interventions for use in inflammatory disease or for resolving pathogen infection." (PMID 33941870, 2021). "Similarly, USP12 knockdown promoted infection of another RNA virus H1N1." (PMID 31899788, 2020).
USP12 also shares sentences with these, for which no sentence is quoted: liver cancer (2 papers); bacterial infection (1); glioma (1); Hurler syndrome (1); mastitis (1); ovarian carcinoma (1); psychiatric diseases (1).